RET (ret proto-oncogene)
Diseases named in the same sentence as RET in open-access papers (continued):
Sharing a sentence is not in itself a finding about the gene and the disease.
pheochromocytoma (continued). "Therefore, the ATA recommends that pheochromocytoma screening (by plasma or 24-hour urine fractionated metanephrines) should begin by age 8 in carriers of RET mutations associated with MEN 2B and mutated RET codons 634 and 630 and by the age 20 years in carriers of other MEN 2A RET mutations." (PMID 24899893, 2014). "We carried out direct sequence analysis of human c-mos and human ENRB in a series of sporadic MTC and phaeochromocytomas to determine if somatic mutations in these two genes could account for some of the sporadic MEN 2-related tumours in which no RET mutations are detected." (PMID 8695346, 1996). "Therefore, we investigated the effect of vandetanib, a representative multi-targeted TKI for RET-related MTC, on cell proliferation and catecholamine synthesis in rat pheochromocytoma PC12 cells." (PMID 40725174, 2025). "MEN2 is a hereditary disease resulting from mutations of the RET protooncogene subclassified into MEN2A (MTC, pheochromocytoma, and primary hyperparathyroidism) and MEN2B (MTC, pheochromocytoma, Marfanoid habitus, mucous neuromas, and intestinal ganglioneuromatosis)." (PMID 39839784, 2024). "Sporadic MTC is defined as MTC in patients without the germline RET mutation, other MEN2-related manifestations, such as pheochromocytoma and hyperparathyroidism, or familial history suggestive of MEN2." (PMID 37835559, 2023). "Though this relationship is not specifically related to a germline variant, RET, SDHB, SDHC, SDHD, and SDHAF2 each include a predisposition of developing pheochromocytoma and thus must be considered." (PMID 35685436, 2022). "Mice with complete absence of functional NF1 develop pheochromocytomas with high penetrance and exhibit higher expression levels of many genes including RET, which is responsible for early development of the central and peripheral nervous systems." (PMID 28187001, 2017). "In this study, it was found that 24% of the patients who presented with nonsyndromic pheochromocytoma and without family history of the disease had mutations in VHL, RET, SDHD, and SDHB genes." (PMID 24899893, 2014). "An allelic imbalance between mutant and wild-type RET may represent the decisive step of tumorigenesis for MTC and pheochromocytoma." (PMID 16707008, 2006). "MEN2A is characterized by bilateral, multicentric MTC in more than 90% of index patients (carrying germline RET mutations in codon 634; i.e. those presenting with MTC at diagnosis in the absence of screening), pheochromocytomas in 50% and primary hyperparathyroidism in 10 to 20%." (PMID 22654562, 2011). "Similarly, in patients with MEN2, a RET germline mutation is necessary for formation of MTC and pheochromocytoma, but may not be sufficient, as there are patients who have never developed MTC or pheochromocytoma during their life or developed MTC late in their lifetime." (PMID 16707008, 2006).
non-small cell lung carcinoma (189 papers, 2012 to 2026). A group of at least three distinct histological types of lung cancer, including non-small cell squamous cell carcinoma, adenocarcinoma, and large cell carcinoma. "Selpercatinib, a selective RET kinase inhibitor, is approved for treating various cancers with RET gene mutations such as RET-rearranged thyroid cancer and non-small cell lung cancer." (PMID 39872362, 2024). "Subsequent next-generation sequencing demonstrated a RET-fusion mutation, leading to reclassification of his malignancy to a sarcomatoid non-small cell lung carcinoma." (PMID 38817847, 2024). "Recently, RET inhibitors have been approved for the treatment of non-small cell lung cancer with RET mutation." (PMID 38407266, 2024). "A handful of smaller retrospective studies have evaluated the use of ICIs in patients with non-small cell lung cancer (NSCLC) who have RET + mutations." (PMID 38317126, 2024). "RET alterations resulting in receptor hyperactivation have been identified as causal factors in multiple neoplastic diseases, most notably non-small cell lung carcinoma (NSCLC) and both medullary and papillary thyroid carcinomas (MTC & PTC)." (PMID 36918928, 2023). "Among the specified types, medullary thyroid cancer, and non-small cell lung cancer (NSCLC) patients have been reported to contain a high frequency of RET mutations." (PMID 35268691, 2022). "RET alterations occur quite frequently as driving mutations or rearrangements in thyroid tumors, but also non-small cell lung cancer and other solid tumors." (PMID 36358717, 2022). "Rearranged during transfection (RET) fusion is a kind of uncommon mutation (about 1%) in non-small cell lung cancer (NSCLC)." (PMID 35692799, 2022). "In RET-rearranged non-small cell lung cancer, both types of resistance mechanisms have been described in patients treated with RET-inhibitors (i.e., RET mutations, KRAS and MET amplification)." (PMID 35600349, 2022). "RET signaling is constitutively activated through mutations in many cancers, notably medullary and papillary thyroid and non-small cell lung cancers, which also have a high rate of hTERT promoter mutations." (PMID 36142729, 2022). "Mutations and fusions of RET (rearranged during transfection) gene are detected in a few common types of tumors including thyroid or non-small cells lung cancers." (PMID 36358717, 2022). "Activating RET mutations and rearrangements have since been identified as actionable drivers of oncogenesis in numerous cancer types and are most prevalent in thyroid and non-small-cell lung cancer." (PMID 38201460, 2023). "Examples include EGFR, ALK, ROS1 and RET alterations in non-small cell lung cancer, rendering tumors susceptible to tyrosine kinase inhibitors, or high microsatellite instability/deficient mismatch repair (MSI-H/dMMR) in gastrointestinal tumors, which is associated with response to PD1 inhibition." (PMID 36687417, 2022). "Thoracic representation was dominated by non-small-cell lung cancer (NSCLC) in RET, NTRK, and HER2 programs (150 patients, 4%), while small-cell lung, mesothelioma, and thymic carcinomas contributed <1% combined." (PMID 41827789, 2026). "Approximately 1−2% of non-small cell lung cancers (NSCLCs) are positive for rearranged during transfection (RET) gene fusions." (PMID 39980547, 2025). "Clinically, selpercatinib’s success in treating RET-altered thyroid and non-small cell lung cancers is attributed to its potent and sustained inhibition of RET signaling." (PMID 41226200, 2025). "Molecular testing revealed a KIF5B-RET gene fusion, classifying her cancer as stage IVB RET-rearranged non-small cell lung cancer (NSCLC)." (PMID 41477385, 2025). "The safety, pharmacokinetics, and efficacy of HA121-28 were assessed in advanced solid tumors (phase 1, ClinicalTrials.gov NCT03994484) and advanced RET fusion-positive non-small-cell lung cancer (RET-TKI naive NSCLC, phase 2, ClinicalTrials.gov NCT05117658)." (PMID 40016191, 2025).
non-small cell lung carcinoma (continued). "In a phase I/II trial (NCT03037385), selective RET inhibitor pralsetinib demonstrated broad antitumor activity in RET fusion-positive solid tumors excluding thyroid and non-small cell lung cancers." (PMID 40980689, 2025). "Beyond EGFR mutations, clinically relevant genetic alterations in non-small cell lung cancer (NSCLC) include fusions involving ALK, ROS1, RET, and NTRK1/2/3." (PMID 41301039, 2025). "Selpercatinib was given to patients with RET fusion-positive non-small cell lung cancer (NSCLC) in the LIBRETTO-001 phase I/II open-label trial (69 patients were treatment naïve, 247 had previously received platinum-based chemotherapy)." (PMID 40332427, 2025). "Selective RET inhibitors such as pralsetinib have become the standard of care for patients with RET fusion-positive non-small cell lung cancer (NSCLC)." (PMID 40702584, 2025). "RET fusions are known to be oncogenic in 1–2% of non-small cell lung cancers, and the clinical trials leading to FDA approval of selpercatinib primarily relied on RECIST criteria to evaluate tumor shrinkage." (PMID 39272672, 2024). "Pralsetinib and selpercatinib are two highly potent and selective rearranged during transfection (RET) inhibitors that substantially improved the clinical outcome of patients with RET-rearranged non-small cell lung cancer." (PMID 38453158, 2024). "The 11 currently reportable or actionable variants for non-small cell lung cancer (NSCLC) were extensively verified (n=126) (ALK, EGFR, BRAF, KRAS, NTRK 1/2/3, ROS, RET, MET, ERBB2)." (PMID 36522176, 2024). "The impact of immune checkpoint inhibitors (ICIs) based treatments on non-small cell lung cancers (NSCLCs) with RET fusions remains poorly understood." (PMID 38317126, 2024). "RET fusions are relatively rare in Non-Small-Cell Lung Cancers (NSCLCs), being around 1–2% of all NSCLCs." (PMID 39199650, 2024). "For instance, RET inhibitors, including pralsetinib and selpercatinib (also referred to as LOXO-292), have been approved for the treatment of RET fusion-positive or mutant non-small cell lung cancer." (PMID 39872362, 2024). "Pralsetinib is a kinase inhibitor indicated for the treatment of metastatic rearranged during transfection (RET) fusion-positive non-small cell lung cancer." (PMID 38675225, 2024). "This case report reports for the first time the benefits of anlotinib and sintilimab for RET fusion and PD-L1 positive non-small cell lung cancer patients." (PMID 39669196, 2024). "The LIBRETTO-001 phase 1/2 trial (NCT03157128) was instrumental in unveiling the efficacy of selpercatinib in managing RET-altered non-small cell lung cancer (NSCLC) and medullary thyroid cancer (MTC), paving the way for its initial regulatory approvals." (PMID 39085487, 2024). "A single-center study from Korea showed two adverse events of extrapulmonary tuberculosis in patients with RET fusion-positive non-small cell lung cancer treated with pralsetinib." (PMID 39600647, 2024). "Pralsetinib is a highly specific inhibitor that targets advanced or metastatic non-small cell lung cancer (NSCLC) characterized by RET-fusion positivity." (PMID 40083593, 2024). "We report the case of a patient affected by metastatic RET-rearranged non-small cell lung cancer who experienced long-lasting disease control with pralsetinib." (PMID 38453158, 2024). "RET fusions were discovered in non-small cell lung cancer (NSCLC), and the efficacy of RET-targeted treatment in these patients has been previously established." (PMID 39372862, 2024). "In adults, RET alterations have been characterized as drivers of non-small cell lung cancer and multiple neuroendocrine neoplasms." (PMID 36918928, 2023). "The frequency of gene RET fusion is a common occurrence in papillary thyroid cancer (10–20%) as well as a subgroup of non-small cell lung cancer (2%), while in other solid tumors such as GC, it is typically found in less than 1% of cases." (PMID 38001751, 2023).
non-small cell lung carcinoma (continued). "Rearranged during transfection (RET) fusions are important genetic drivers in non-small cell lung cancer (NSCLC)." (PMID 35838839, 2023). "The ALK, ROS1 and RET kinase fusion are crucial biomarkers that can predict the function of tyrosine kinase inhibitors (TKIs) in the non-small-cell-lung cancer (NSCLC)." (PMID 37091783, 2023). "Rearranged during transfection (RET) fusion-positive occurs in approximately 2% of non-small cell lung cancer (NSCLC)." (PMID 37603207, 2023). "RET-kinase-activating gene rearrangements occur in approximately 1–2% of non-small-cell lung carcinomas (NSCLCs)." (PMID 37445709, 2023). "Systemic therapies for RET fusion-positive non-small cell lung cancer consist mostly of targeted therapy with RET inhibitors such as selpercatinib and pralsetinib." (PMID 37478265, 2023). "In this study, seven articles reported ORR in previously treated or untreated RET fusion gene-positive non-small cell lung cancer patients treated with RET-TKIs." (PMID 37603207, 2023). "RET is an oncogene involved in the development of thyroid malignancies, non-small-cell lung carcinomas (NSCLCs) and several other categories of neoplasms." (PMID 37445709, 2023). "Genomic rearrangement of RET occurred in 1–2% of non-small cell lung cancer (NSCLC) and had been confirmed as an oncogenic driver in NSCLC." (PMID 38057798, 2023). "ARTN, RET, and GFRα3 have been demonstrated to be upregulated in non-small cell lung carcinoma (NSCLC) cells compared with their normal counterparts, while high ARTN expression also enhances the migration and invasion of NSCLC cells." (PMID 35582425, 2022). "The RET inhibitors, selpercatinib and pralsetinib have were also approved for the treatment of RET-fusion non-small cell lung cancer." (PMID 36167530, 2022). "RET fusions can be found in 1–2% of non-small-cell lung cancers (NSCLCs), approximately 20% of papillary thyroid cancers and <1% of many other solid tumors, including ovarian, pancreatic, salivary and colorectal cancers." (PMID 35962206, 2022). "Rearranged during transfection (RET) is an oncogenic driver receptor that is overexpressed in several cancer types, including non-small cell lung cancer." (PMID 35268691, 2022). "Patients with RET fusions represent 1-2% of all cases of non-small cell lung cancer (NSCLC), the majority of whom are younger, and are extremely rare in the elderly." (PMID 36568233, 2022). "More recently, RET fusions have emerged as significant genomic targets in non-small cell lung cancer and other carcinomas." (PMID 34282751, 2021). "Patients with non-small cell lung cancer (NSCLC) often harbor driver mutations in multiple oncogenes, including EGFR, RAS, ALK, ROS1, BRAF, HER2, RET, etc.." (PMID 34975346, 2021). "The ARROW clinical trial (Phase 1/2) reported that the response rate of pralsetinib in treatment-naive RET-altered non-small cell lung cancer patients was 73% (95% CI: 52%–88%), and the response rate in treated patients was 61% (95% CI: 50%–72%)." (PMID 34497761, 2021). "RET rearrangements are observed in 1–2% of non-small-cell lung cancer (NSCLC) patients and result in the constitutive activation of downstream pathways normally implied in cell proliferation, growth, differentiation and survival." (PMID 34503226, 2021). "Rearranged during transfection (RET) fusions are found in 0.7% to 2% of non-small cell lung cancer (NSCLC)." (PMID 34743497, 2021). "REarranged during Transfection (RET) is an emerging target for several types of cancer, including non-small cell lung cancer (NSCLC)." (PMID 33806299, 2021). "Rearranged during transfection (RET) is a tyrosine kinase oncogenic receptor, activated in several cancers including non-small-cell lung cancer (NSCLC)." (PMID 34834190, 2021). "Rearranged during transfection proto-oncogene (RET) fusions represent a potentially targetable oncogenic driver in non-small cell lung cancer (NSCLC)." (PMID 32183422, 2020).
non-small cell lung carcinoma (continued). "Rearranged during transfection (RET) has been proven to be a tumorigenic target in non-small cell lung cancers (NSCLCs)." (PMID 32295619, 2020). "The dawn of the targeted therapy era saw the discovery of receptor tyrosine kinase RET fusion in 1–2% of non-small cell lung cancers (NSCLC) and proved it to be tumorigenic and targetable." (PMID 32295619, 2020). "These genes are frequently mutated in non-small cell lung cancer (NSCLC) with variable frequencies: EGFR, ALK; ROS1 and RET." (PMID 32928143, 2020). "The possibility that RET fusions drive resistance to EGFR inhibition is corroborated by recent studies showing that RET fusions confer resistance to osimertinib in non-small cell lung cancer patients." (PMID 31653970, 2019). "Another selective RET kinase inhibitor, BLU-667, was assessed in a phase 1 study involving RET positive non-small cell lung cancer and thyroid cancer." (PMID 31058838, 2019). "Recent studies identified more specific and potent RET inhibitors such as Sitravatinib, which are currently evaluated in thyroid and non-small cell lung cancer." (PMID 30621641, 2019). "Vandetanib, the first generation RET inhibitor, has shown activity in patients with advanced non-small cell lung cancer harboring RET rearrangements." (PMID 29262623, 2017). "Rearranged during transfection (RET) fusion-positive non-small cell lung cancer (NSCLC) accounts for approximately 1–2% of all NSCLCs." (PMID 29088743, 2017). "KIAA1217-RET, resulting from the rearrangement of chromosome 10, was generated by the fusion of KIAA1217 exon 11 and RET exon 11 from a non-small cell lung cancer patient." (PMID 27150058, 2016). "Case Presentation: A 47-year-old female with metastatic RET fusion-positive non-small cell lung cancer (NSCLC) presented with progressive dyspnea and digital ischemia despite strict adherence to therapeutic anticoagulation with rivaroxaban for a prior pulmonary embolism." (PMID 41893435, 2026). "RET fusions are rare, and occur in 1%-2% of all non-small cell lung cancer (NSCLC) patients." (PMID 41695350, 2026). "Furthermore, acquisition of TK fusions, such as ALK or RET fusions, have been also reported during targeted therapy in non-small cell lung cancer (NSCLC) and other tumors, as a mechanism of resistance." (PMID 38877018, 2024). "The research of lenvatinib on KIF5B RET positive adenocarcinoma of the lung has entered phase II (nct01877083), and its clinical experiments combined with pembrolizumab on non-small cell lung cancer has entered phase III (nct03829332, nct04676412, nct03976375)." (PMID 38164168, 2024). "Oncogenic RET gene fusions have been identified in non-small cell lung cancer and non-medullary thyroid cancers, whereas RET point mutations are the key genetic finding in both inherited and sporadic MTC." (PMID 38469239, 2024). "However, RET fusion has been commonly reported in papillary thyroid and non-small cell lung cancers." (PMID 36865807, 2023). "Oncogenic alternation in RET is one of the important targets of non-small cell lung cancer (NSCLC)." (PMID 37924363, 2023). "RET rearrangements are rare, and occur in 1%-2% of all non-small cell lung cancer (NSCLC) patients." (PMID 35223529, 2022). "RET fusions are rare, occurring in 1%-2% of all patients with non-small cell lung cancer (NSCLC)." (PMID 35223529, 2022). "RET fusions are rare oncogenic drivers in non-small cell lung cancer (NSCLC)." (PMID 36059009, 2022). "However, as previously exposed, data on response rates are not as impressive as other targeted agents, such as RET inhibitors in RET-fusion positive non-small-cell-lung cancer, for example." (PMID 33451055, 2021). "Approximately 50% of the RET-altered non-small cell lung cancer patients were found to have developed brain metastasis, but the intracranial responses of pralsetinib that were tested in the patient group with brain metastasis revealed a satisfactory response rate of 56%." (PMID 34497761, 2021).